TIGIT (T cell immunoreceptor with Ig and ITIM domains)
Diseases named in the same sentence as TIGIT in open-access papers (continued):
Sharing a sentence is not in itself a finding about the gene and the disease.
tumor (continued). "Similarly, we did not observe any difference in IFNγ or TNFα production between TIGIT+ and TIGIT− NK cells in response to cytokine stimulation, suggesting that these TIGIT+ NK cells have greater anti-tumor but not general responsiveness." (PMID 37345049, 2023). "Furthermore, KIF18A expression was positively correlated with many common immune checkpoints, including PD-L1, PD-1, CTLA4, TIGIT, HAVCR2, PDCD1LG2, and LAG3, indicating that KIF18A may be a new target for tumor immunotherapy." (PMID 36830695, 2023). "Interestingly, in the present study, no significant changes in the surface phenotype were observed after tumor exposure, including similar DNAM-1 expression, and a trend toward decreased expression was only observed for NKG2D, with some improvement with TIGIT blockade." (PMID 37345049, 2023). "In addition, TIGIT has been found to bind three ligands, namely CD155 (PVR), CD112 (PVRL2, nectin-2), and CD113 (PVRL3), which are expressed by tumor cells, antigen-presenting cells, and also T-lymphocytes in the tumor microenvironment." (PMID 36765782, 2023). "However, PD-1, TIGIT, and CTLA-4 are highly expressed in the TILs of TNBC patients, while PD-L1 and CD155 ligands are highly expressed in tumor cells or antigen presenting cells (APCs), which may make CD8+ T cells inefficient at killing tumor cells." (PMID 35770416, 2023). "Furthermore, TIGIT appears to have the capability of altering T cell metabolism via the blockade of glycolysis and work in conjunction with hypoxia-inducible factor 1-α (HIF1-α) to increase tumor cell invasion, colony formation, and angiogenesis." (PMID 37291608, 2023). "However, the presence of NK cells is typically reduced in established tumors because of the elevated expression of inhibitory receptors, such as TIGIT, CD96, and TIM3, on tumor-infiltrating NK cells, leading to a substantial impairment of their anti-tumor functionality." (PMID 37876793, 2023). "Direct T cell inhibition through TIGIT’s ITIM domain, and its similarity to other IgG superfamily members such as PD-1, suggested that blocking TIGIT in TMEs could relieve an inhibitory signal to reinvigorate exhausted tumor-specific memory T cells." (PMID 38022590, 2023). "Priming the tumour with the appropriate neoadjuvant chemoradiotherapy treatment could lead to higher immune infiltrations and higher expression of immune checkpoints, such as PD-1/PDL-1, CTLA4 or emerging new targets: LAG-3, TIM-3, TIGIT or ICOS." (PMID 38155973, 2023). "ADAM2 also restricts expression of the immune checkpoint inhibitors PDL1, LAG3, TIGIT and TIM3 in the tumor microenvironment, which might explain why ex vivo expanded and adoptively transferred cytotoxic T-cells show enhanced cytotoxic efficacy in ADAM2 overexpressing tumors." (PMID 37258521, 2023). "Patients with high TIGIT and/or CD155-expressing tumor may benefit from TIGIT blockade better." (PMID 37441080, 2023). "CD8 Tex with elevated expression of multiple inhibitory receptors (PDCD1, CTLA4, LAG3, TIGIT, HAVCR2) and Tregs with high expression levels of FOXP3, TIGIT, and CTLA4 were enriched in the ESCC TME, which contributed to tumor immune escape and immunotherapy resistance." (PMID 37187751, 2023). "Given that TIGIT is highly expressed on activated, tumor-infiltrating NK cells and at lower levels on resting non-activated NK cells, Fc-competent anti-TIGIT antibodies could lead to the depletion of this critical population through FcR-dependent mechanisms." (PMID 37345049, 2023). "In addition, other studies in HCC tissue found a negative correlation between the levels of expression of TIGIT and the degree of tumor progression." (PMID 37999131, 2023). "However, in one study, immunofluorescence staining of bone marrow sections of MM mice showed that Treg cells were highly accumulated at the tumor location, and expressed higher levels of CD25, ICAM-1, CD69, CD44 and co-inhibitory receptors Lag-3, Tim-3, TIGIT and PD-1." (PMID 38129374, 2023).
tumor (continued). "In addition to this pro-tumorigenic function, CD155 plays an immunomodulatory role during tumor progression since it is a ligand for both the activating receptor DNAM-1 and the inhibitory receptor TIGIT, expressed on cytotoxic innate and adaptative lymphocytes." (PMID 37629138, 2023). "Both TIGIT and CD96 inhibit NK and T cell function via binding to CD226, indicating a possibility that ITGAL may suppress NK and CD8+ T cell’s killing activities of tumor cells." (PMID 37835514, 2023). "In summary, our findings support the hypothesis that blockade of TIGIT combined with RT enhances host anti-tumor immunity in a non-redundant DC-dependent manner and that the presence of DCs may be critical for the function of certain immunotherapies." (PMID 35794399, 2023). "Importantly, it was able to sensitize tumor cells to TIGIT blockade therapy, although low-dose OX alone failed to inhibit the growth of tumor cells." (PMID 36389751, 2022). "Most previous reports documenting TIGIT expression have evaluated immune cells, not tumor cells." (PMID 35971106, 2022). "Furthermore, TIGIT, LAG-3, HAVCR2 (TIM-3), and IDO1 are known as novel immune checkpoint targets that can suppress the activation of effector T lymphocytes, hence mediating a tumor immune escape mechanism." (PMID 35416526, 2022). "Here, we showed that the expressions of PD-1, Tim-3 and TIGIT on Vγ9Vδ2+ T cells and CD8+ T cells are regulated by the 1α,25(OH)2D3/VDR signaling pathway, which contributes to T-cell cytotoxicity under the condition of tumor-antigen and T-cell receptor (TCR) activation." (PMID 35318258, 2022). "Therefore, we conducted a meta- and bioinformatic analysis in this article for the following purposes: 1to evaluate the prognostic value of TIGIT in OS, DFS, PFS, and RFS and 2 to determine the relationship between TIGIT expression and the tumor microenvironment and immune microenvironment." (PMID 36211383, 2022). "Therefore, we further compared the expression of immune checkpoint genes in tumor tissues of the high SIRGs score group and the low SIRGs score group and found that PD-L1, CTLA-4, HAVCR2, LAG3, TIGIT and PDCD1 were also up-regulated in the high SIRGs score group." (PMID 36052090, 2022). "Furthermore, low-dose CIS treatment combined with anti-TIGIT mAb did not delay tumor progression or increase overall survival." (PMID 36389751, 2022). "Consistent with expectations, the upregulation of inhibitory receptors (PD1, TIGIT) and XBP1 was observed when coculturing CD8+ T cells with the supernatant of BTC cells, suggesting that ER stress and exhausted CD8+ T cells were induced and formed in the tumor microenvironment." (PMID 35982235, 2022). "Moreover, when PD1, LAG3, and TIGIT were inhibited in tandem with NBTXR3-enhanced radiation, there was also a robust and unambiguous elevation of genes involved in macrophage activation, enhanced trafficking, tumor phagocytosis, and antigen presentation." (PMID 36123677, 2022). "However, when exposed to tumor antigens for a long time, the expression of tumor suppressors such as PD-1, CTLA4, TIGIT, TRIM3, and LAG3 in the microenvironment will be significantly upregulated, which will lead to impaired killing function and exhaustion of CD8+ T cells." (PMID 36422531, 2022). "And TIGIT could bind to CD155, CD112, and CD113, which are ligands on tumor cells." (PMID 36309698, 2022). "In addition, the combined blockade of TIGIT and PD-1 further increased the level of infiltrating CD8+ T lymphocytes in the tumour tissue and secretion function factors TNF-α and IFN-γ by CD8+ T lymphocytes compared with the group subjected to TIGIT blockade alone." (PMID 35729552, 2022). "Following the accomplishments of PD-1 and CTLA-4 inhibitors, others targeting TIGIT, Tim-3, Lag3 and NKG2A are currently being explored in some solid tumors in various pre-clinical and clinical trials, in order to promote effective anti-tumor immunity with clinical benefits." (PMID 36077799, 2022).
tumor (continued). "Tumor cells can escape the killing of tumor cells by T cells through downregulating MHC and upregulating the expression of inhibitory receptors such as PD-L1, CTLA-4, LAG-3, TIM-3 and TIGIT, and blocking the binding of these inhibitory receptors to ligands can restore T-cell anti-tumor activity." (PMID 36225938, 2022). "Similarly, researchers utilized superparamagnetic iron oxide-based NPs (SPIONs) combined with chitosan lactate (CL) and folic acid (FA) nanoparticles (NPs) loaded with TIGIT-siRNA and HIF-1α-siRNA for suppressing TIGIT and HIF-1α in tumor cells in another study." (PMID 36532768, 2022). "Moreover, through the link with Fibroblast activation protein 2 (Fap2), a Fusobacterium nucleatum derived protein, TIGIT triggers a negative signal that suppress T and NK cells activities, thus mediating a tumor-immune evasion mechanism." (PMID 36551630, 2022). "Supervised flow cytometry analyses showed that (i) most CD3+ TILs expressed PD-1 and TIGIT and, to a lesser extent, Tim-3, Lag3 and NKG2A, and (ii) EpCAM+ tumor cells and CD11b+ myeloid cells differed in their IC ligand expression profile, with a strikingly high expression of CD155 by tumor cells." (PMID 36077799, 2022). "These receptors are involved in processes such as tumor promotion and generation of metastasis; overexpression of these ligands contributes to immunological evasion through their interaction with T cell immunoglobulin and ITIM domain (TIGIT), an inhibitory receptor present on some NK and T cells." (PMID 35465350, 2022). "When the dose of oxaliplatin was reduced from 6 mg/kg to 1.5 mg/kg, the synergism of the combination treatment was observed; nevertheless, a single injection of low-dose OX or anti-TIGIT could not delay tumor growth or increase overall survival." (PMID 36389751, 2022). "Our research found that, besides fibroblasts, endothelial cells, and some tumor cells, CD155 is also highly expressed on BMSCs, and we demonstrated that BMSCs might directly inhibit NK cell function through the TIGIT/CD155 pathway, leading to NK cell depletion." (PMID 36303184, 2022). "TIGIT is mainly expressed on the surface of activated T cells and NK cells, and its receptors are primarily poliovirus receptors (PVR, CD155) and VR-like protein 2 (PVRL2, CD122), which are highly expressed in tumor cells and APCs, and are newly discovered immune checkpoint ligands." (PMID 35892835, 2022). "However, the TIGIT-related communication was a little stronger within hypoxia T cells, while tumor necrosis factor (TNF)- and FASLG-related communications were stronger in normoxia between T cells and tumor cells." (PMID 34956900, 2021). "Notably, CRC tumor-infiltrating Tregs can be distinguished by the increased expression of a panel of signature markers, including CD30, IL1R2, IL21R, OX40, CCR8, PD-L1, TIGIT, and 4-1BB." (PMID 33527196, 2021). "Additionally, it induced a lower frequency of tumor-infiltrating CD8+ T cells expressing TIGIT and TIM3, which suggested that NK cells expressing TIGIT might also indirectly contribute to the exhaustion of CD8+ T cells." (PMID 34367161, 2021). "Moreover, azelnidipine could not only block the TIGIT/PVR pathway, but also reduce the expression of PVR, which may further enhance the anti-tumor effects." (PMID 34068552, 2021). "We reported that blockade of TIGIT/PVR by peptide could elicit strong tumor tissue penetration ability and anti-tumor immune response, even in anti-programmed cell death protein 1 (PD-1) resistant tumor model." (PMID 33557880, 2021). "TIGIT and CD96 are expressed on the surface of T cells and natural killer cells and represent targets for immune modulation, as blocking CD96 or TIGIT with monoclonal antibodies improves tumor control in mice, especially when used in combination with PD-1/PD-L1 blockade." (PMID 33796453, 2021).
tumor (continued). "Together, these data suggest that upregulated expression of TIGIT and PD1 may confer immunosuppression and tumor aggression in GBM patients through both shared and distinct pathways, and therefore targeting both these pathways may be beneficial for improving clinical outcome of GBM patients." (PMID 34025646, 2021). "Additionally, TIGIT signaling in Tregs upregulates CCR8 which may promote Treg migration and retention in tumor tissue." (PMID 34367161, 2021). "Importantly, there were no changes in tumor size observed in the CA septic mice treated with anti-TIGIT mAb; these findings are consistent with a previous study in which anti-TIGIT treatment alone did not impact tumor size over a prolonged period of time." (PMID 34100383, 2021). "The importance of the Fc domain of anti-TIGIT mAb is emphasized by the findings that anti-TIGIT mAb with Fc devoid of effector functions, which was intended to solely block TIGIT binding to its ligands, fails to exert any of anti-tumor efficacies in preclinical models." (PMID 33670993, 2021). "Interestingly, RBCK1 showed significant differential expression between cancer and normal tissues and was significantly related to tumor-infiltrating immune cells, including tumor purity and immune checkpoint molecules such as PD-L1, CTLA-4, LAG-3, and TIGIT in ccRCC." (PMID 34795663, 2021). "Interestingly, hierarchical clustering of non-ccRCC tumours revealed that TIGIT cluster was rather majority and prominent in a subset of non-ccRCC." (PMID 34545095, 2021). "There is evidence that T cells lose their effector function and ability to kill tumor cells when stimulated by tumor antigens, which may be due to the increasing diversity and number of inhibitory receptors, including CD274, PDCD1LG2, HAVCR2, CTLA4, LAG3, PDCD1, TIGIT." (PMID 33592580, 2021). "However, TIGIT blockade with either anti-PD-1/PD-L1 or TIM-3 showed a synergistic effect with a slowdown of tumor growth but no remission was observed." (PMID 34572799, 2021). "In conclusion, both TIGIT and CD96 were demonstrated to negatively regulate NK cell activity, and preventing the binding of these receptors with their ligands could benefit NK cell-mediated anti-tumor functions." (PMID 33572396, 2021). "Otherwise, tumor cells in hypoxia could inhibit TAMs activation via HLA-G/LILRB interactions, assist TAMs polarization via CD44-related communication, and inhibit T-cell activation via PDCD1 and TIGIT." (PMID 34956900, 2021). "In our study, the CT26 subcutaneous tumor was confirmed as a “cold” tumor with little CD8+ T cell infiltration, which may partly explain the limited anti-tumor efficacy of the monotherapy with TIGIT blockade in the previous studies." (PMID 33581644, 2021). "It has been speculated that CD155 expression leads to tumor immunosuppression, because the interaction of CD155 with TIGIT or CD96-positive T lymphocytes and NK cells results in exhaustion of immune function, in addition to reducing the secretion of interferon-γ." (PMID 34115802, 2021). "In addition to binding to CD155, TIGIT can bind to CD112, and both receptor-ligand interactions inhibit NK cytotoxicity directly through the ITIM motif, which inhibits the NK-mediated killing of tumor cells." (PMID 34433460, 2021). "However, a study observed that TIGIT blockade or TIGIT knockdown alone exerted no substantial effect on tumor growth and metastasis." (PMID 34943817, 2021). "By ligand interaction, TIGIT is able to inhibit lymphocytes activity through different mechanisms of action including modulation through its intracellular tail after binding to PVR, induction of PVR signaling in adjacent dendritic or tumor cells, and inhibition of CD226 signaling." (PMID 33782477, 2021). "We found that VV-α-TIGIT can completely clear the tumor cells and produce long-term immune memory in the ascites tumor model, whereas it could not completely clear the tumor in subcutaneous tumor models." (PMID 33581644, 2021).
tumor (continued). "In summary, these new data suggest that immunosuppressive myeloid cells, and presumably MDSCs, suppress anti-tumor immunity by inhibiting antigen-specific T cell function in GBM, at least in part via TIGIT and PD1 pathways, which may have major implication to patient treatments by immunotherapy." (PMID 34025646, 2021). "Interestingly, blockade of TIGIT in NK cells alone appeared necessary for the most potent anti-tumor responses mediated by CD8+ T-cells, and generated a memory response against secondary tumor challenge." (PMID 32153582, 2020). "In addition, TIGIT, but not other checkpoint molecules, such as CTLA-4 and PD-1, was linked to NK cell exhaustion in tumor-bearing mice and patients with CRC." (PMID 33419310, 2020). "On the other hand, great progress has achieved in discovering novel immune checkpoints which could also synergize with PD-1/PD-L1 and were non-redundant in restricting the anti-tumor response of immune cells, such as TIGIT, LAG-3, TIM-3 and CD47." (PMID 32894141, 2020). "Levels of TIM-3, CTLA-4, TIGIT, TOX, TOX2, and SIRT1 genes in tumor tissue were significantly higher than that of the circulation; their expressions within the TME could be induced by tumor-mediated immunosuppression." (PMID 32393998, 2020). "Furthermore, treatment of TIGIT KO mice with the anti-TIGIT:mIgG2a antibody did not provide any further benefit to tumor growth inhibition, demonstrating the specificity of the anti-TIGIT antibody." (PMID 33117369, 2020). "Our observations reported in this work demonstrate that Fc engagement is necessary and required for anti-tumor efficacy of antagonist anti-TIGIT antibodies, and that blocking the TIGIT:CD155 interaction alone is not sufficient to confer anti-tumor efficacy of antagonist anti-TIGIT antibodies." (PMID 33117369, 2020). "This may suggest that elevated expression of PD-1, TIM-3, CTLA-4, TIGIT, TOX, TOX2, and SIRT1 genes in the TME of CRC is induced by tumor-associated, factors, unlike VISTA, and LAG-3." (PMID 32393998, 2020). "It has been reported that anti-PD-L1 and anti-TIGIT (a novel immune checkpoint inhibitor) combination therapy improved overall survival in GBM patients by increasing effector T cell function and downregulating the number of suppressive Tregs and tumor-infiltrating dendritic cells." (PMID 32765489, 2020). "The antagonistic anti-TIGIT antibody OMP-313M32 (NCT03119428) was evaluated as a single drug, and two antibodies were combined with PD-1 blockers to evaluate MTIG7192A (NCT02794571) and BMS-986207 in some advanced primary brain tumours or other primary tumours (NCT02913313)." (PMID 32461587, 2020). "However, when looking at the expression level, we observed relatively high expression of LAG3 and HAVCR2 in both primary and recurrent tumor and a trend of greater expression for TIGIT, CTLA4, BTLA, and PDCD1 in recurrent tumor tissue, compared to primary tumor tissue (NS)." (PMID 33352957, 2020). "This could suggest that T cells expressing CTLA-4 and TIGIT accumulate in the circulation of CRC patients during the onset of disease, until they are recruited to the TME as disease progresses, resulting in their accumulation within the tumor tissue." (PMID 32393998, 2020). "Moreover, TIGIT blockade prevented NK cell exhaustion in the absence of adaptive immunity, and elicited a potent T cell–mediated memory response to tumor re-challenge through a not yet identified mechanism." (PMID 31105707, 2019). "Studies have shown that other immune checkpoints such as TIGIT, LAG-3, and TIM-3 may play a role in promoting tumor immune evasion and exhaustion of virus-specific T cells, suggesting that combination ICI therapy may need to be explored to effectively treat both cancer and chronic viral infection." (PMID 31847881, 2019).